MCAM (melanoma cell adhesion molecule)
Description:
Plays a role in cell adhesion, and in cohesion of the endothelial monolayer at intercellular junctions in vascular tissue. Its expression may allow melanoma cells to interact with cellular elements of the vascular system, thereby enhancing hematogeneous tumor spread. Could be an adhesion molecule active in neural crest cells during embryonic development. Acts as a surface receptor that triggers tyrosine phosphorylation of FYN and PTK2/FAK1, and a transient increase in the intracellular calcium concentration.
Synonyms: CD146; MUC18; MelCAM; METCAM; HEMCAM
Tractability: Antibody: a drug acting on it is in phase 1 trials; UniProt predicts a signal peptide or a membrane-spanning region; its Gene Ontology location is reachable by antibodies, with medium confidence; the Human Protein Atlas places it where antibodies can reach. PROTAC: ubiquitination databases record sites on it; its protein half-life has been measured.
Target class: Adhesion
Gene: Protein-coding gene on chromosome 11 (119,307,972 to 119,321,521, reverse strand). Ensembl gene ENSG00000076706.
Subcellular location: Membrane
Subcellular location (Human Protein Atlas): Plasma membrane
Pathways (Reactome):
Signal Transduction: RAC1 GTPase cycle; RAC2 GTPase cycle; RAC3 GTPase cycle; RHOA GTPase cycle; RHOB GTPase cycle; RHOC GTPase cycle; RHOD GTPase cycle; RHOF GTPase cycle; RHOG GTPase cycle
Gene Ontology:
Molecular function: protein binding
Biological process: angiogenesis; glomerular filtration; vascular wound healing; anatomical structure morphogenesis; cell adhesion; positive regulation of cell migration
Cellular component: external side of plasma membrane; extracellular region; focal adhesion; plasma membrane; membrane
Genetic constraint (gnomAD): Loss-of-function variants: 55 observed, 79.22 expected, observed/expected ratio (o/e) 0.69, 90% interval 0.56 to 0.87. The upper end of that interval is the gene's LOEUF score, 0.87, which puts it in group 3 of 6, group 1 being the genes least tolerant of losing a copy. Missense variants: 740 observed, 860.47 expected, observed/expected ratio (o/e) 0.86, 90% interval 0.81 to 0.91. Synonymous variants: 328 observed, 350.04 expected, observed/expected ratio (o/e) 0.94, 90% interval 0.86 to 1.03.
Homologues: Orthologues: chimpanzee MCAM (99% identical), macaque MCAM (96% identical), pig MCAM (84% identical), dog MCAM (80% identical), mouse Mcam (76% identical), rat Mcam (76% identical), guinea pig MCAM (75% identical), rabbit MCAM (72% identical), tropical clawed frog mcam (34% identical), zebrafish mcama (34% identical), zebrafish mcamb (30% identical). Paralogues in human: BCAM (28% identical), ALCAM (20% identical), AGER (15% identical).
Diseases named in the same sentence as MCAM in open-access papers:
MCAM is named in the same sentence as 253 diseases in open-access papers, as found by Europe PMC text mining. Sharing a sentence is not in itself a finding about the gene and the disease. The quoted sentences say what the papers report.
melanoma (266 papers, 2005 to 2026). A malignant, usually aggressive tumor composed of atypical, neoplastic melanocytes. "Here we revisit the potential association of MCAM, a member of the immunoglobulin superfamily that was initially identified as a melanoma antigen, with disease progression." (PMID 39945026, 2025). "These markers include melanoma-associated chondroitin sulfate proteoglycan, melanoma cell adhesion molecule, NKI/beteb, NKI/C3, and high-molecular-weight melanoma-associated antigen (MHW-MAA)." (PMID 38724687, 2024). "Whilst MCAM had previously been implicated in the interaction of melanoma cell‐derived EVs with endothelial cells, this represents, to our knowledge, the first description of an involvement of PECAM1 in EV uptake by endothelial cells." (PMID 39400522, 2024). "Many previous studies have shown that MCAM activation in melanoma cells is closely associated with the induction of AKT signalling." (PMID 36291660, 2022). "In this study, galectin-3 was shown to be naturally associated with MCAM in melanoma cells, and their interaction promotes melanoma cell proliferation, adhesion, migration, and invasion, all of which are important steps in melanoma progression." (PMID 36291660, 2022). "MCAM is highly expressed in various malignancies and has tight association with their growth and metastasis, such as melanoma, prostate cancer, gastric cancer, and lung cancer." (PMID 36618348, 2022). "Suppression of MCAM expression was associated with significant reduction of melanoma cell proliferation." (PMID 36291660, 2022). "It is therefore not surprising that binding of galectin-3 to the highly glycosylated MCAM in melanoma cells also causes MCAM clustering on the cell surface." (PMID 36291660, 2022). "These indicate that MCAM and galectin-3 are naturally associated on the cell surface of melanoma cells." (PMID 36291660, 2022). "Other metastasis-associated factors on melanoma cells that affect the tumor microenvironment include MCAM/MUC18, L1-CAM, α4β1-integrin, ECM remodeling molecule FN1, and glypican-6." (PMID 35008286, 2021). "For example, galectin-3 binds to N-linked glycans on CD146/MCAM (Melanoma Cell Adhesion Molecule) and induces CD146 dimerization and subsequent activation of AKT (Protein kinase B) signaling." (PMID 32517158, 2020). "Our recent in vivo study demonstrated the antitumor and antivascular effects of intratumoral GET with plasmid DNA-encoding shRNA against MCAM in melanoma B16F10, which resulted in significant tumor growth delay and 17% of tumor cures." (PMID 32204304, 2020). "Here, a microfluidic device is devised conjugated with melanoma cell adhesion molecule (MCAM) and melanoma‐associated chondroitin sulfate proteoglycan (MCSP) for isolation and molecular profiling of both melanoma CTCs and exosomes." (PMID 33042766, 2020). "CREB (cAMP response element-binding protein) and its associated proteins (e.g., MMP-2, MCAM and MUC18) play a key role in tumor growth and metastasis of human melanomas." (PMID 29377892, 2018). "They then concluded that MART-1/ MLANA and ABCB5 are helpful in following high-risk melanoma patients confirming that MCAM/MUC18/CD146 expression is associated with poorer outcome in stage IV disease." (PMID 28280601, 2017). "Stromal progenitors in human BM that reside in the sub-endothelial layer of sinusoids strongly express the melanoma-associated adhesion molecule (MCAM/CD146)." (PMID 25364727, 2014). "Taken together, sequential molecular detection of MCAM/MUC18 seems to identify a subset of high-risk melanoma patients with poor prognosis." (PMID 24902661, 2014). "MCAM expression on CTCs in melanoma patients has been associated with increased tumor burden and poorer outcome in Stage IV disease." (PMID 24069584, 2013). "Involvement of PAX3 in melanoma migration is further supported by evidence showing that other genes associated with cell migration, including MCAM, CSPG4, and CXCR4, are targeted by PAX3, as shown by ChIP assay in A2058 melanoma cells." (PMID 24069584, 2013).
melanoma (continued). "For example, MCAM (also called CD146, Mel-Cam, Muc18, and S-Endo1) has been implicated in the progression of melanoma, as well as in breast and prostate cancer." (PMID 22272201, 2012). "The cell adhesion molecule MCAM has been associated with melanoma progression and metastatic potential." (PMID 20421967, 2010). "Up-regulation of MCAM, together with loss of keratinocyte-dependence, is one of the crucial events that allows melanoma cells to invade the dermis and progress to vertical growth phase." (PMID 20421967, 2010). "CD146 (MCAM) is associated with an advanced tumor stage in melanoma, prostate cancer and ovarian cancer." (PMID 19123925, 2009). "Prior studies have focused on using CellSearchTM kits that were developed to isolate CTCs that express melanoma cell adhesion molecule (MCAM) from blood samples and detect CTCs by immunostaining with melanoma-associated chondroitin sulphate proteoglycan (MCSP)." (PMID 39156972, 2024). "MCAM has been considered to be associated with tumor development in human malignant melanoma." (PMID 36739428, 2023). "The expression of MCAM is associated with poor treatment outcome of melanoma patients." (PMID 36291660, 2022). "Recently, two MCAM/MUC18/CD146 isoforms have been described, a long and a short variant due to alternative splicing: the short isoform is widely expressed by the endothelium, whereas the long isoform is expressed by melanoma cells." (PMID 32548126, 2020). "In vitro, silencing with plasmid DNA-encoding shRNA against MCAM reduced MCAM at mRNA and protein levels for different degrees in different cells, melanoma, endothelial cells, and breast cancer cells, with the highest silencing in melanoma and the lowest in endothelial cells." (PMID 32204304, 2020). "Nevertheless, a variety of markers associated with some melanoma-specific cell-surface epitopes have been proposed, such as MCAM/MUC18/CD146 and MSCP/NG2 (melanoma-associated chondroitin sulfate), together with stem cell markers, such as ABCB5 (ATP-binging cassette subfamily member B) and CD271." (PMID 32548126, 2020). "For detecting CTCs, some of the previous melanoma CTCs markers used include melanoma-associated chondroitin sulfate proteoglycan, melanoma cell adhesion molecule (CD146), NKI/beteb and NKI/C3, and high-molecular-weight melanoma-associated antigen (MHW-MAA)." (PMID 33585560, 2020). "Linked by a network of overlapping functions in melanoma progression, melanoma cell adhesion molecule (MCAM), galectin-3 (Gal-3), chondroitin sulfate proteoglycan 4 (CSPG4), matrix metalloproteinase 2 (MMP-2), and paired box 3 (PAX-3) potentially act as biomarkers and targets in melanoma metastasis." (PMID 33490091, 2020). "Similarly, cysteine point mutations that block MCAM palmitoylation increases metastatic cell behavior in melanoma cells both in vitro and in vivo." (PMID 29648538, 2018). "The KLK7‐mediated loss of E‐cadherin and gain in MCAM/CD146 may suggest a possible role of KLK7 in melanoma cell aggregation, a known mechanism of chemoresistance in cancer." (PMID 28636767, 2017). "Another study reported that inhibiting MCAM expression in melanoma cells may lead to loss of gap-junction communication, as evidenced by reduced invasion in a three-dimensional skin reconstruct model." (PMID 26703751, 2015). "MCAM/MUC18 is a cell adhesion molecule associated with higher incidence of relapse in melanoma." (PMID 24902661, 2014). "Despite the overwhelming evidence that MCAM expression on a melanoma lesion is associated with a poor prognosis, details of the key molecular interactions in melanoma progression that involve MCAM remain unclear." (PMID 24069584, 2013). "Therefore, the loss of this transcription factor during melanoma results in high MCAM/MUC18 levels and c-KIT downregulation." (PMID 23634303, 2013).
melanoma (continued). "From these reviews and others we have identified five melanoma biomarkers consistently associated with melanoma progression – melanoma cell adhesion molecule (MCAM), galectin-3 (Gal-3), matrix metalloproteinase-2 (MMP-2), chondroitin sulfate proteoglycan 4 (CSPG4), and paired box 3 (PAX3)." (PMID 24069584, 2013). "In addition to melanoma, MCAM expression has been linked to progression of breast, prostate, and ovarian cancer." (PMID 24069584, 2013). "For example, melanoma cells exposed to Wnt5a (a cell polarity-associated signaling molecule) in the presence of a chemokine gradient formed an intracellular structure containing actin, myosin, and MCAM." (PMID 22272201, 2012). "Several multiple marker RT-PCR assays have been demonstrated and proposed as sensitive methods to evidence circulating melanoma cells (CMCs) in peripheral blood of melanoma patients through the detection of one or more melanoma-associated markers (MAMs) of differentiation which include MCAM/MUC18." (PMID 24902661, 2014). "Melanoma cell adhesion molecule (MCAM) (CD146) was first identified as a melanoma tumor marker in 198713." (PMID 41407823, 2025). "We also stained sections of melanoma skin and lymph node metastases derived from 42 patients and found MCAM expression to be slightly increased compared to primary melanomas." (PMID 39945026, 2025). "Initially, MCAM was described as an adhesion molecule by finding that melanoma cells bound to MCAM purified from melanoma cells in the solid phase." (PMID 41388158, 2025). "Over the past 35 years, extensive literature that describes the expression of MCAM across various tumors has been published, including the first report identifying it in malignant melanoma cells." (PMID 41388158, 2025). "In melanoma, the interaction between MCAM and Galectin-3 promotes tumor progression by activating the AKT signaling pathway." (PMID 40221534, 2025). "These multifunctional molecules often act as cell surface receptors, are overexpressed in cancer, and represent potential immunotherapy targets [for example, ALCAM-CD166; melanoma CAM (MCAM)-CD146/Mucin 18, CXADR]." (PMID 40314078, 2025). "While MCAM+ lymphocytes bind to laminin 411 to enter tissues and promote inflammatory and autoimmune reactions, MCAM+ cancer cells, including melanoma cells, bind to laminin 421 to induce cancer metastasis via vascular and lymphatic vessels." (PMID 40332051, 2025). "CD146, also known as MUC18 or MCAM, was first identified in malignant melanoma and plays an important role in driving melanoma progression and metastasis." (PMID 40032820, 2025). "Another example is the cell adhesion molecule MCAM also known as MUC18 or CD146, which is linked to metastasis and poor prognosis in melanoma and other malignancies." (PMID 40768895, 2025). "Subsequent studies reported an increase of MCAM expression in melanoma cells during metastatic disease progression." (PMID 39945026, 2025). "First experimental evidence for a tumour promoting role of MCAM was obtained through transgenic overexpression of MCAM in the melanoma cell line SB‐2, which resulted in an accelerated tumour growth of MCAM overexpressing cells after transplantation in mice." (PMID 39945026, 2025). "Bioinformatic inference of cellular communication networks reveals that melanoma cells with high MCAM expression more actively engage in signalling crosstalk with endothelial cells." (PMID 39945026, 2025). "We quantified the expression of MCAM in tumour cells, taking into account both the stain area and intensity, and observed MCAM expression in most melanomas." (PMID 39945026, 2025). "MCAM is overexpressed on the surface of CTCs, playing an important role in the metastatic progression of melanoma; it can also be used to identify/quantify CTCs and therefore be a predictor of treatment response." (PMID 40507830, 2025). "As expected, we detected high expression levels of MCAM in melanoma cells, endothelial cells and pericytes." (PMID 39945026, 2025).
melanoma (continued). "Bioinformatic inference of cellular communication networks revealed that melanoma cells with high MCAM expression more actively engage in signalling crosstalk with endothelial cells." (PMID 39945026, 2025). "Using immunohistochemical stainings and bioinformatic analyses of published datasets, we find abundant MCAM expression both in primary and metastatic human melanomas." (PMID 39945026, 2025). "In 2002, ABX-MA1, the MCAM monoclonal antibody (mAb), was reported to inhibit tumorigenesis and metastasis in melanoma in the xenografted mouse model; however, in the case of osteosarcoma, it did not stop tumor growth but prevented metastasis." (PMID 41388158, 2025). "MCAM (melanoma cell adhesion molecule) was discovered and described in 1987 by Johnson and co-workers in the plasma membrane of human melanoma cells." (PMID 41388158, 2025). "In 2017, a monoclonal antibody called TsCD146 mAb was shown to reduce the membrane expression of MCAM on melanoma and pancreatic cancer cells by up to 25%." (PMID 41388158, 2025). "MCAM (melanoma cell adhesion molecule), identified in human melanoma in 1987, has garnered attention due to its diverse roles in development, homeostasis, and various diseases, including cancer." (PMID 41388158, 2025). "Wnt5a-induced depalmitoylation of melanoma cell adhesion molecules (MCAM) promoted melanoma cell invasion ability." (PMID 38315203, 2024). "Even more upstream, the crucial early role of these alarmins was revealed in inducing pneumotropic metastasis of melanoma cells via their interaction with melanoma cell adhesion molecules in the framework of the S100A8/A9‐MCAM axis." (PMID 38775220, 2024). "Although MCAM is less expressed in malignant tumors and benign nevi, it can be highly specifically expressed in melanoma cells and has been shown to be an independent predictor of melanoma prognosis." (PMID 37427124, 2023). "CMCs isolation was based on immunomagnetic enrichment of CD45 depleted, about 99.98% of leukocytes are depleted, by virtue of melanoma-specific CD146/MCAM and ABCB5 antigen expression." (PMID 37511550, 2023). "The protein was originally assumed to be only expressed in melanoma; thus, it was also named MelCAM or MCAM." (PMID 36672713, 2023). "These monoclonal antibodies target the CD146 antigen, also known as MCAM or Muc18, which is found on the surface of various cell types, including endothelial cells, melanoma cells, immune cells, and pericytes." (PMID 37959540, 2023). "Low rate of surface expression of CD146, known as melanoma cell adhesion molecule is considered as another senescence marker." (PMID 38111010, 2023). "The CD146 molecule was first described as Melanoma Cell Adhesion Molecule (MCAM); this protein is highly upregulated in melanoma and was shown to mediate adhesion to EC." (PMID 37138793, 2023). "Over the past years, increasing evidence has demonstrated that MCAM expression plays a vital role in melanoma progression and metastasis." (PMID 36291660, 2022). "Other groups have documented the generation of a scFv against MUC18, a cell surface receptor known as melanoma cellular adhesion molecule (MCAM) and whose altered expression affects the motility and invasion processes in breast cancer." (PMID 36077739, 2022). "Despite more and more studies reporting the importance of MCAM expression and activation in melanoma progression and metastasis, the natural binding ligand that induces MCAM activation in melanoma so far remains largely elusive." (PMID 36291660, 2022). "More and more evidence has shown that activation of the MCAM on cell surface plays a vital role in melanoma progression and metastasis." (PMID 36291660, 2022). "Amongst the long list of potential markers, we selected CD146, a receptor originally identified as a melanoma cell adhesion molecule." (PMID 35892560, 2022).